CXCL8 (C-X-C motif chemokine ligand 8)
Diseases named in the same sentence as CXCL8 in open-access papers (continued):
Sharing a sentence is not in itself a finding about the gene and the disease.
glioma (continued). "Targeting CXCL8 in combination with other treatments may improve therapeutic outcomes in gliomas with high CXCL8 expression, offering a promising approach for treating HGG." (PMID 41432874, 2025). "Future studies integrating transcriptomic data from TMZ-treated glioma samples may help clarify whether CXCL8 expression influences drug response, thereby enhancing its clinical relevance." (PMID 41432874, 2025). "This study showed that high CXCL8 expression negatively correlated with survival in patients with glioma, suggesting that CXCL8 could be a potential biomarker of disease progression and prognosis." (PMID 39488622, 2024). "CXCL8 expression is negatively correlated with survival prognosis in gliomas." (PMID 39488622, 2024). "Therefore, the present study aims to investigate the mechanism of action of glioma cells in a methionine-restricted environment by activating the transcriptional expression of CXCL8 to promote angiogenesis." (PMID 39488622, 2024). "The results of the survival curves showed that in high-grade gliomas, the survival of the high-expression group of CXCL8 was significantly shorter, whereas in low-grade gliomas, the high-expression CXCL8 group showed a poorer prognosis only in the CGGA-693 cohort." (PMID 39488622, 2024). "These database analyses suggest that CXCL8 expression levels are negatively correlated with survival prognosis in high-grade gliomas and may predict poor prognosis in high-grade gliomas." (PMID 39488622, 2024). "Nevertheless, it remains unclear how CXCL8 affects methionine metabolism and angiogenesis and its relationship to the prognosis of glioma patients." (PMID 39488622, 2024). "Secretion and positive cellular expression for CXCL8 and its specific receptors were exhibited in glioma cells, neurons, neutrophils, macrophages, lymphocytes, endothelial cells, and glial cells; thus, each of these cell types may contribute to gliomagenesis." (PMID 35269652, 2022). "A bioinformatics analysis of glioma cohort data showed that HK-II overexpression in gliomas was prognostic with the up-regulation of already known associated markers with tumor progression/recurrence (such as VEGF, CXCL8, and HIF1A)." (PMID 35677429, 2022). "Additionally, higher CXCL8 expression was associated with increased production of proteolytic enzymes, particularly MMP-2 and -9, which also contribute to the enhanced glioma cell invasion." (PMID 35269652, 2022). "CXCL8 contributes to angiogenesis and tumor progression in glioma through the AP-1/NF-kB axis." (PMID 35011369, 2021). "Moreover, it was suggested that CXCL8 produced by malignant cells is critical to glial tumor progression and neovascularity." (PMID 34200145, 2021). "Moreover, TAMs play a proangiogenic role in the tumor and secrete another proangiogenic chemokine, CXCL8, which additionally contributes to the progression of glioma." (PMID 34200145, 2021). "It was also revealed that glioma grade strongly correlates with the levels of CXCL8." (PMID 32456359, 2020). "Indeed, not only CSF levels of CXCL8, but also their indices were significantly elevated in patients with CNS tumors as compared to the non-tumoral control group, what may confirm the potential usefulness of these types of samples in the diagnostic process of glioma management." (PMID 32456359, 2020). "Moreover, TAMs play a pro-angiogenic role in the tumor and secrete CXCL8, contributing additionally to the progression of glioma." (PMID 32456359, 2020). "Similarly to other malignancies, an upregulation of CXCL8 in tumor cells was observed also in gliomas." (PMID 32456359, 2020). "Importance of upregulated CXCL8 level in glioma was considered by many researchers." (PMID 32456359, 2020). "Thus, CXCL8 is highly expressed in gliomas, and its level may be correlated with the degree of malignancy." (PMID 39488622, 2024).
glioma (continued). "Based on the TCGA database, the CGGA database, and clinical tissue samples, CXCL8 expression was significantly higher in glioma tissues than in non-tumor tissues, and its expression was significantly higher in high-grade glioma tissues than in low-grade glioma tissues." (PMID 39488622, 2024). "Consequently, CXCL8 may be an essential molecular therapeutic target for gliomas in the future." (PMID 39488622, 2024). "A 44-plex cytokine array (Luminex) revealed glial cells are a major source of pro-tumorigenic CCL2 while glioma cells express CXCL1 and CXCL8." (PMID 35906273, 2022). "The significance of up-regulated interleukin-8 (IL-8/CXCL8) and its receptors (CXCR1, CXCR2) levels in glioma was explored by many researcher groups." (PMID 35269652, 2022). "In T98G, Hs683, and U373 glioma cells, the expression and secretion of CXCL2, CXCL3, and CXCL8 were measured after various temozolomide (TMZ) treatments." (PMID 35269652, 2022). "Therapeutic stress increases CXCL8 and CXCR2 expression, enhancing glioblastoma tumorigenicity, growth, and therapy resistance by inducing glioma-initiating cell formation." (PMID 35011369, 2021). "The upregulation of CCNB1, CDK1, CXCL8, IGFBP3, MYBL2, SERPINE1 also notably indicated poor overall survival of glioma patients (HR>1, P=0.000<0.05)." (PMID 34512164, 2021). "CXCL8 and CXCR2 tumor expression is related to glioma grade, disease-free survival, and OS in GBM, and their upregulation in high-grade glioma correlates with resistance to anti-angiogenic therapy." (PMID 34638384, 2021). "It was demonstrated that CXCL8 participates in this cellular process by activating the JAK/STAT1/HIF-1α/Snail signaling pathway in glioblastoma cells, thus promoting glioma progression." (PMID 32456359, 2020). "These actions of CXCL8 are additionally increased by the expression of proteolytic enzymes, especially MMP-2 and -9, which also contribute to the enhanced glioma cell invasion." (PMID 32456359, 2020). "It was recently revealed that enhanced CXCL8 expression in the tumor microenvironment might also contribute to the local and systemic immunosuppression induced by glioblastoma, which allows GBMs to evade host immunosurveillance and may create a significant barrier to glioma immunotherapy." (PMID 32456359, 2020). "U87 glioma cells express several chemokines (CCL2, CCL20, CXCL1, CXCL2, CXCL8, etc.), among which IL-8 is the most abundant after radiation." (PMID 31488817, 2019). "In glioma cells, TPCA-1 and BMS-345541 inhibited NF-κB activation and CXCL8 gene expression, as well as IFN-activated gene expression." (PMID 30413032, 2018). "Among these proteins, interleukin-8 (IL-8, or CXCL8) is now known to be a major promoter of angiogenesis and invasiveness of human gliomas, where it is expressed and secreted at high levels." (PMID 26449498, 2015). "In accordance with our study, Burcu also found that VEGFA and CXCL8 were significantly overexpressed in patients with glioma, and that both VEGFA and CXCL8 could promote angiogenesis and accelerate the progression of LGG to GBM." (PMID 39488622, 2024). "Interestingly, we found that most of these ligands (e.g., CSF1, CXCL8, POSTN) 21, 32, 43 are broadly expressed in different glioma subclusters, whereas SPP1 is specifically expressed in the CEBPB+ GBM subcluster." (PMID 38994023, 2024). "We identified an increase in CXCL1, CXCL8, and CCL2 upon combining glioma cells with glial cells." (PMID 35906273, 2022). "In addition to evaluating individual biomarker performance, future studies should also explore whether combined expression patterns of CXCL8 and THBS1 could improve discriminatory power between glioma grades." (PMID 41432874, 2025). "Importantly, a subset of these human-derived cytokines that included CXCL10, IL-33, CXCL8, KITLG, CCL2, and TGFα were not secreted or secreted at very low levels in vitro by BT147 cells, suggesting that the increased secretion was the result of a glioma–host cell interaction within the brain." (PMID 33020472, 2020).
diabetes (209 papers, 2008 to 2026). "Expression analysis of diabetes-associated DEGs such as CXCL8, IL7R, and NR4A1 showed significant alterations after 20(R)-Rg3 treatment." (PMID 41373625, 2025). "Notably, IL-6 has been linked to diabetes and cardiovascular events, while CXCL8 has been associated with an unfavorable metabolic and lipid profile in type 2 diabetes." (PMID 41030257, 2025). "In db/db and Akita mice, CXCL15, a functional equivalent of CXCL8, is increased in β cells at the early stages of diabetes, concomitant with an increase in islet macrophages." (PMID 36001973, 2022). "In male mice with diabetes, the CXCL8 antagonist is evident to enhance diabetic nephropathy and attenuate high glucose-induced mesangial injury." (PMID 34725640, 2021). "As a result, CXCL8 might be a crucial target for the management and prevention of gout patients with diabetes mellitus or CVD." (PMID 38686389, 2024). "Taken together, IL-8/CXCL8 and IL-18 appear related with depressive symptoms irrespectively of diabetes status." (PMID 39799156, 2025). "In vivo, upregulations in circulating macrophage CXCL1 expression, a homologue of CXCL8, were observed in spontaneously diabetic biobreeding (BB) rats and in a streptozotocin (STZ) -induced diabetes mouse model." (PMID 40718478, 2025). "Gene Set Enrichment Analysis revealed that CXCL8, IL1B, and CCL2 have significant potential in diabetes." (PMID 38167125, 2024). "The GSEA analysis further demonstrated the pivotal roles of CXCL8, IL1B, and CCL2 in diabetes through immune and inflammatory mechanisms." (PMID 38167125, 2024). "In contrast, among subjects with diabetes, mRNA expression of TIMP1 and CXCL8 was significantly higher in subjects with PN, and positively correlated with MNSI-PE scores (rho = 0.469, p = 0.001; rho = 0.454, p = 0.002)." (PMID 35651981, 2022). "In our analysis, including subjects with diabetes, mRNA levels of TIMP1 and CXCL8 were significantly higher in subjects with PN compared with their counterparts." (PMID 35651981, 2022).
endometriosis (201 papers, 2005 to 2026). The growth of functional endometrial tissue in anatomic sites outside the uterine body. "Nevertheless, we confirmed our previous results as well as other laboratories that endometriosis is associated with elevated peritoneal CXCL8." (PMID 34501240, 2021). "Cytokines like IL6 and CXCL8/IL8 are found at abnormal levels in endometriosis and affect neutrophil recruitment and alter the peritoneal cavity microenvironment." (PMID 41009445, 2025). "Although CXCL8 showed high expression in endometriosis, all adjacent tissue showed intense staining as well." (PMID 39373851, 2024). "In the current study, we found that CXCL8 expression was higher in endometriosis than in normal endometrium." (PMID 35303800, 2022). "In the study of human endometriosis, progesterone (10−6 mol/L) was found to be effective in attenuating TNFα/estrogen-induced expression of CXCL8 in endometriotic stromal cells." (PMID 35476705, 2022). "CXCL8 was reported to be involved in all processes in the development of endometriosis, including adhesion, invasion, and implantation of the ectopic tissues." (PMID 35303800, 2022). "Interleukin-8 (IL-8) and monocyte chemotactic protein 1 (MCP-1), encoded by CXCL8 and CCL2 respectively, showed higher expression levels in the eutopic endometrium of women with endometriosis." (PMID 35130311, 2022). "Endometriosis was also associated with elevated concentrations of IL-6, IL-10, and TGF-β1/2 as well as CCL20, CXCL8, CXCL9, and CXCL10." (PMID 34501240, 2021). "Secretion of CXCL8 is significantly higher in the eutopic endometrial stromal cells from women with endometriosis than that in the control." (PMID 32334621, 2020). "The most studied chemokine in endometriosis is IL-8 (also called CXCL 8), which in a systematic review had the best potential among chemokines as a diagnostic marker for endometriosis." (PMID 30621017, 2019). "This may be associated with increased concentrations of neutrophil chemoattractants, such as epithelial neutrophil-activating peptide-78 (ENA-78) and IL-8 (CXCL8), in peritoneal fluid and serum of patients with endometriosis, respectively." (PMID 41488658, 2025). "The concentration of CXCL8 in the peritoneal fluid of patients with moderate/severe endometriosis was also higher than that of patients with mild endometriosis, indicating that CXCL8 might be important in endometriosis development." (PMID 35303800, 2022). "The correlation index of FN1 vs. five kinds of immune cells was greater than 0.5 and the correlation coefficient between aDCs and CXCL8 was the highest, indicating a close interplay between the immune/inflammatory response and endometriosis development and progression." (PMID 35303800, 2022). "The correlation of aDCs with CXCL8 was the highest, suggesting that FN1 and CXCL8 (IL-8) may promote the infiltration of immune cells and change the local immune microenvironment during the development of endometriosis." (PMID 35303800, 2022). "CXCL-8 levels are elevated in peritoneal fluid in women with endometriosis." (PMID 17506907, 2007). "Furthermore, glandular epithelial cell localisation and upregulation of immunoreactive CXCR1 and CXCR2, which bind CXCL8, has been demonstrated in eutopic and ectopic tissue sections from endometriosis patients when compared to controls." (PMID 17506907, 2007). "CXCL8 (IL-8), another chemokine whose mRNA was increased in endometrial glands from women with endometriosis in our array study, has previously been studied in depth with regard to a role in endometriosis, further substantiating our gene array results." (PMID 17506907, 2007). "Neutrophils aggravate endometriosis mainly through the expression of pro-inflammatory cytokines such as interleukin 8 (IL-8 or CXCL8), C-X-C motif chemokine ligand 10 (CXCL10) and vascular endothelial growth factor (VEGF), which may promote disease progression." (PMID 37446108, 2023).
endometriosis (continued). "However, whether endometriosis depends on CXCL8 to regulate the immune microenvironment in the development of endometriosis requires further study." (PMID 35303800, 2022). "CXCL8 played a crucial role by binding to CXCR1 and activating the PTEN/AKT pathway, thereby promoting proliferation and inhibiting apoptosis in endometriosis cells." (PMID 40757199, 2025). "Among the top genes in the two key subnetworks, VEGFA, CXCL8, CCL2, IL1B and PTGS2 were also considered to be highly related to endometriosis in MalaCards." (PMID 35130311, 2022). "Concentrations of IL-6, IL-10, CCL2, CXCL8 and CXCL9 were significantly upregulated in the PF from women with endometriosis when compared to control women, whereas concentrations of other cytokines and chemokines were unaffected." (PMID 34360900, 2021). "The levels of some investigated cytokines and chemokines, such as IL-6, IL-10, CCL2, CXCL8, and CXCL9, were significantly increased in PF from patients with endometriosis as compared to control." (PMID 34360900, 2021). "The evaluation of chemokines showed that the peritoneal fluid from patients with endometriosis displayed significantly higher concentrations of CCL20, CXCL8, CXCL9, and CXCL10." (PMID 34501240, 2021). "PF from the women with endometriosis displayed significantly increased concentrations of CCL2, CXCL8 and CXCL9 as compared with the control subjects." (PMID 34360900, 2021). "Consistently, patients with endometriosis displayed a significant higher production of CXCL1, CXCL2, and CXCL8 in the peritoneal fluid as compared to those from controls." (PMID 32334621, 2020). "Certain chemokines, especially CXCL8 (IL-8), CCL-2 (MCP-1), and CCL5 (RANTES), can serve as biomarkers identifying patients with endometriosis, but the accuracy of such tests can be improved by including other noninflammatory markers in the biomarker panel." (PMID 27294113, 2016). "Although little is known of the role of CXCL8 in endometrial cancer, dysregulated CXCL8 and CXCR2 expression has recently been proposed to play a role in other endometrial disorders such as endometriosis." (PMID 19819266, 2009). "Suppressing the CXCL8 and CXCL12/CXCR4/CXCR7 axis prevents the development of inflammation in both PCOS and endometriosis, which may help to improve the prognosis of disorders associated with inflammation." (PMID 41009445, 2025). "Previous studies also reported that CXCL8 expression was significantly higher in the peritoneal fluid of endometriosis patients than that of patients without endometriosis." (PMID 35303800, 2022).
depression (200 papers, 2006 to 2026). "Using a multivariate linear model, high serum levels of MIP-1β/CCL4 and Eotaxin/CCL11 remained associated with depression (p < 0.01), while, IL-8/CXCL8, MIP-1β/CCL4, MCP-1/CCL2, and MIP-1α/CCL3 were associated with anxiety (p < 0.05) in the symptomatic groups." (PMID 34863117, 2021). "A global gene co-expression network analysis found genes related to immune response, acute inflammatory response, and C-X-C motif chemokine ligand 8 (IL8) receptor activity to be associated with antidepressant response using three independent cohorts of patients with depression." (PMID 37772416, 2023). "Further studies are needed to demonstrate that other chemokines, such as CCL4, CXCl4, CXCL7 and CXCL8, proposed as being altered in depression are also sensitive to CBT interventions." (PMID 31974503, 2020). "Finally, we observed a differential expression of iRNAPII-BRs and nearby genes—ADRB2, CXCL8, SFN, and GPR3—in major depressive disorder, indicating that iRNAPII-BR-associated transcription may contribute to the pathophysiology of this disorder." (PMID 41446805, 2025). "Notable exceptions include CCL11 that has recently been shown to impair hippocampal function in aging – of distinct relevance to Alzheimer’s disease and depression in the elderly, and pre-natal exposure to CXCL8 that may disrupt early neurodevelopmental periods predisposing to schizophrenia." (PMID 26441528, 2015). "For this purpose, the correlation between the cytokines VEGF, CCL5, CXCL8 and CXCL10 and BMI, depression, anxiety and stress was assessed while controlling for the neuropathy." (PMID 28811623, 2017). "Notably, IL-6, IL-1RA, IL-12, TNF-α, IFN-γ, IL-10, IL-1β, and IL-8/CXCL8 exhibit increased levels in both acute and chronic CHIKV cases, as well as in depression." (PMID 38088664, 2023). "Analysis of the clinical utility of the effect size of plasma CXCL8 in healthy individuals found a negative predictive value 93.5%, given the population prevalence of depression of 10%." (PMID 29133955, 2018). "This meta-analysis indicates that a number of these chemokines (CCL2, CCL3, CCL4, CCL11, CXCL4, CXCL7 and CXCL8) when measured in the blood discriminate between those with and without depression." (PMID 29133955, 2018). "The second major finding of this study is that depression is accompanied by increased production of the Th-1, Th-2, Th-17, and Treg cytokines and partial activation of the M1 phenotype (increased production of TNF-α, sIL-1RA, and CXCL8) as compared with healthy controls." (PMID 35455402, 2022).